AR (androgen receptor)
Diseases named in the same sentence as AR in open-access papers (continued):
Sharing a sentence is not in itself a finding about the gene and the disease.
tumor (continued). "Therefore, AR expression was analyzed in more than 18,000 tumor tissue samples from 141 different tumor types and subtypes as well as 76 different non-neoplastic tissue types by immunohistochemistry (IHC) in a tissue microarray (TMA) format in this study." (PMID 38790919, 2024). "Immunohistochemistry of liver metastatic biopsies and PDX tumor showed lack of expression of typical PCa (e.g., AR, PSA, PSAP, ERG) or neuroendocrine markers (synaptophysin), compatible with double-negative CRPC, but was positive for nuclear β-catenin expression, keratin 7 and 34βE12." (PMID 38907236, 2024). "Other evidence suggests that the AR might be a tumor suppressor in ERα -positive (BC, but a tumor promoter in ERα negative BC." (PMID 37979099, 2024). "Prostate adenocarcinoma may transdifferentiate via NED into neuroendocrine prostate cancer (NEPC), a more aggressive and advanced tumour, induced by treatments including ADT or other therapies targeting components of the AR signalling pathway such as ADRB2 activation." (PMID 37830741, 2023). "In summary, our data suggest that antiandrogen resistance may give rise to colonies of GR-upregulated PCa cells within the tumor where l-CaD expression is induced in response to GR activation in the absence of AR signaling." (PMID 37573448, 2023). "Surgical orchiectomy plus enzalutamide with anti-PD-L1 antibodies led to significant tumor regression and increased the overall survival rate in either an androgen deprivation therapy plus anti-PD-1-resistant mouse prostate tumor model or an AR-negative mouse sarcoma tumor model." (PMID 36880651, 2023). "In localized PC patients, who were not androgen‐ deprived, SLPI expression and AR expression were positively correlated and may have affected tumor growth; nevertheless, further research is needed." (PMID 36812122, 2023). "Therefore, androgen-independent disease was hypothesized to be attributed to SGTA overexpression in dog-PCa-patient tumor samples by some researchers, who also subsequently showed that interference with SGTA dimerization in vitro rescues AR signaling." (PMID 37189720, 2023). "In CRPC, several hypotheses suggest how the AR promotes cell growth and tumor progression, even without the presence of testosterone or DHT." (PMID 37894767, 2023). "In ERα-positive malignancies, AR may be a tumor suppressor, while in ERα-negative tumors, AR may be a tumor promoter." (PMID 37626712, 2023). "Additionally, mitochondrial AR localization, by reducing OXPHOS levels, may prevent the potential stimulatory effects exerted by BAD on complex I activity, shown to promote tumor growth." (PMID 37686282, 2023). "In other words, tumor biology in mCRPC may not be as aggressive in a patient with only an AR amplification compared to those whose malignancy has multiple GAs that include AR (such as MYC, BRAF, PIK3CA, and others)." (PMID 38450313, 2023). "The mechanism that would explain the relationship between PCSC and CRPC would involve the expansion of a residual AR-negative/low stem-like cell population remaining after androgen deprivation and potentially repopulating tumors with castrate-resistant tumor cells." (PMID 37189723, 2023). "However, these approved treatments do not cure CRPC, because they do not affect those residual castration resistant prostate CSCs, which do not depend on AR signal pathways and cannot be detected in the tumor tissue or measured in the blood by PSA." (PMID 38067237, 2023). "Although potent AR pathway inhibitors (ARPIs), such as enzalutamide, abiraterone acetate and apalutamide, have therapeutic effects on CRPC, these tumors almost inevitably develop AR-independent pathways to sustain tumor growth after the long-term usage of ARPIs." (PMID 37240468, 2023). "AR expression increases with tumor grade, regardless of sex." (PMID 37626712, 2023). "However, not all castration resistance is dependent on AR signaling because of the tumor’s variety, heterogeneity, and flexibility." (PMID 36902032, 2023).
tumor (continued). "Very low AR signaling activities led to little or no AR-target expression in the hybrid tumor." (PMID 37848444, 2023). "Therefore, to identify whether FOXA1 and HOXB13 are colocalized with AR in the regulatory regions (−5 kb/+2 kb from TSS) of the DE-lncRNAs, we used previously published FOXA1 and HOXB13 ChIP-seq data in PCa tumor samples." (PMID 37140987, 2023). "Combined inhibition of AR and PARP by olaparib plus enzalutamide decreased the proliferation of PC cells in xenograft PC model mice after 1 week of treatment, suggesting that the combination may synergistically inhibit tumor growth." (PMID 37152924, 2023). "However, several studies have not detected significant differences in tumor AR expression between genders." (PMID 38283839, 2023). "Interestingly, in contrast to the prominent NE tumor phenotype in DKO prostates, TKO prostates displayed an evident expression of luminal cell markers CK8 and AR and a downregulation of the NE marker SYP, supporting a function of ADORA2A in modulating PCa cellular plasticity." (PMID 38099497, 2023). "In addition, flow cytometry results demonstrated that AR knockdown induced increased apoptosis and G1/S phase arrest in tumour cells treated with DTX in vivo.Conversely, FEN1 overexpression reversed apoptosis and G1/S phase arrest induced by DTX and AR knockdown." (PMID 37326412, 2023). "Androgen receptor (AR) signaling could promote the transition from stem cell-like CD8+ T cells to terminally exhausted CD8+ T cells in male mice, and it was correlated with tumor-infiltrating CD8+ T cell exhaustion in cancer patients." (PMID 36880651, 2023). "Moreover, in PCa cell lines, the AR antagonist bicalutamide (BCT) increased ARO expression and ERβ transcriptional activity; indeed, in CRPC, ARO expression was significantly increased in tumor samples." (PMID 35457011, 2022). "In DuCaP, AR-V7 levels did not increase relative to AR, suggesting that the differential expression of AR variants upon ADT/ARTA may occur but not in every tumor per se." (PMID 35769712, 2022). "Furthermore, we introduced a novel therapeutic combination of ceritinib and paclitaxel for AR negative or AR-low TNBCs and this combination inhibited tumor growth to a great extent." (PMID 35768871, 2022). "We hypothesized that a responding tumor factor would have a higher extent of surrounding stromal AR-positive (sAR(+)) cells, while non-responding tumor factors would be encircled by sAR(−) cells." (PMID 36115838, 2022). "Tumor plasticity driven by continual stepwise targeting of AR has garnered recent attention and may lead to AR negative cells driven by fibroblast growth factor (FGF) or neuroendocrine transdifferentiation mechanisms." (PMID 36358940, 2022). "However, resistance to ADT occurs almost inevitably, leading to lethal castration-resistant PCa (CRPC), in which AR continues to drive tumour growth in the absence of circulating androgens." (PMID 35159022, 2022). "However, AR expression was negatively associated with PFS in Xp11.2 tRCC patients but not the age of onset, patient sex, tumour size, tumour stage or pathological grade." (PMID 35452181, 2022). "Also, CPPI at a 50 mg/kg/day dose suppressed tumor growth in LNCaP but not PC-3 cell-derived xenograft models with or without castration, indicating an AR-specific effect." (PMID 35372068, 2022). "Besides, a recent study illustrated that androgen receptor (AR) could inhibit the formation of vasculogenic mimicry of HCC and influence tumor metastasis by AR-circRNA7/miRNA7-5p/VE-Cadherin/Notch4 signaling." (PMID 35361205, 2022). "Using the same dosage of AZD4547 as that in NCI-H1581 xenograft-bearing mice for 4 days, tumor growth could not be inhibited in NCI-H1581/AR xenografts." (PMID 36168616, 2022). "However, later studies failed to observe a difference in AR mRNA expression between tumor and peritumoral tissue." (PMID 36430245, 2022).
tumor (continued). "To evaluate the potential tumor-suppressive effect of ZBTB10 in downregulating PKLR-driven PCa progression, we used a stable ZBTB10-expressing clone and compared it to ZBTB10-expressing cells rescued with the PKLR cDNA vector in AR-positive LNCaP and C4-2 cells." (PMID 35306527, 2022). "Indeed, AR and ESR1 were identified as the targets of the sex hormones testosterone and estradiol, respectively, whereas HDACs and BRDs were suppressed upon treatment with the anti-tumor drugs vorinostat and JQ1." (PMID 35073843, 2022). "Additionally, many studies have demonstrated that fatostatin, nelfinavir, AR antagonist, natural compounds, or herbal extracts can target SREBP-1 and its downstream targets for the inhibition of lipid biosynthesis in tumor growth and progression of various cancers." (PMID 35912181, 2022). "Further analysis revealed that CPPI blocked AR nuclear import and promoted AR degradation in the nuclear compartment through MDM2-dependent proteasome mechanism in CRPC cells (C4-2 and LNCaP95) and xenograft tumor models, leading to sharp retardation of tumor growth." (PMID 35372068, 2022). "Moreover, elevated expression of KLK3, prostate-specific antigen (PSA) gene in T cells (AR-negative) was observed, attributed to extracellular vesicle/exosome-mediated trafficking from the tumor cells to T cells." (PMID 35669415, 2022). "During this period, tumor evolution shaped by systemic therapy exposure to androgen deprivation therapy (ADT), docetaxel chemotherapy and/or potent androgen receptor pathway inhibitors (ARPI) mean that archival tissue may not reflect the contemporaneous tumor genotype." (PMID 36439451, 2022). "Neither the bare Au nanoparticles nor the Au‐Peptide Control had a therapeutic effect on tumor growth, the Au‐AR DBD PROTAC showed great efficiency in both the C4‐2 and CWR22Rv1 xenograft models, and enzalutamide inhibited tumor growth in the C4‐2 but not the CWR22Rv1 xenograft model." (PMID 35971165, 2022). "Here, we demonstrate that in the presence of ER, AR may not be functioning as a mediator of radioresistance, suggesting that AR inhibition is not an effective radiosensitisation strategy in women with tumours expressing high levels of AR and ER." (PMID 35618789, 2022). "Unlike full-length AR, the tumor levels of the splice variant AR-V7 did not correlate to time on ARAT, although the association of AR-V7 mRNA expression in circulating tumor cells with time to ARAT resistance and clinical outcome has been reported in other studies." (PMID 35205640, 2022). "Based on these results, we provide evidence that miR-378 does play a crucial role in inhibiting PCa tumor proliferation, and it might be increased through EPA stimulation in PCa tumor cells, which further downregulates the activities of KLK genes to block the AR signaling pathway." (PMID 35681793, 2022). "Hence, our data and results from prior reports suggest that testosterone with AR and ERα could promote CRC development, while E2 and P4, alongside ERβ and PGR, may act as tumour suppressors." (PMID 36263327, 2022). "Sequencing of chromatin immunoprecipitation using an anti-AR antibody (AR-ChIP seq) revealed distinct profiles of AR binding site (ARBS) in androgen-dependent and castration-resistant xenograft tumors compared with those previously reported based on human PCa cells or tumor tissues." (PMID 35365763, 2022). "In patient samples, high AR activity was similarly required for anti-tumor activity of BAT, as there was no patient with a low ARAMW score (defined by our cut-off of less than 0.6) who exhibited significant downregulation of MYC and/or clinical evidence of tumor regression by BAT." (PMID 36194476, 2022).
tumor (continued). "Also, the non-luminal tumors AR+ showed lower tumor size and lower prognostic stage but frequently higher grade and higher HER2 intensity of expression (3+)." (PMID 35052843, 2022). "In MCF7 (ER+ AR+) xenograft tumors, enzalutamide blocked E2–driven tumor proliferation as strongly as tamoxifen, suggesting that high AR/ER may not simply result from low ER expression, but that AR itself does play a role in tumor cell proliferation." (PMID 36556209, 2022). "A subset of tumor cells from CRPC patients receiving ADT or current AR pathway inhibition (ARPI) therapy may progress to an AR-negative phenotype, and this is considered to result from an accumulation of neuroendocrine (NE) and stem cell characteristics." (PMID 35306527, 2022). "Women with estrogen receptor (ER) positive, AR positive (ER+AR+) tumors are known to have better survival and more favorable clinicopathological features, like negative lymph node metastasis and lower tumor grade than women whose tumors are negative for AR." (PMID 34234742, 2021). "Moreover, a cross-talk between PARP1 and androgen receptor (AR) function has been proposed as the basis of the benefit of the combination of PARPi with AR inhibitors regardless of the HRD status of the tumour." (PMID 35008208, 2021). "Interestingly, A-485 potently inhibits proliferation of AR+ cells, but not AR— cells in vitro, and reduces in vivo tumor growth of AR+ xenografts." (PMID 34201346, 2021). "Also, GnRH analogs counteracted the tumor growth of androgen receptor (AR)-negative DU145 xenografts, further supporting their direct and reproductive system-independent anti-cancer effects." (PMID 34743733, 2021). "Furthermore, the AR agonist enobosarm, a selective AR modulator (SARM), have been proposed to reduce tumor growth in preclinical studies, but a clinical trial using different doses of it did not confirm previous results, when administered in postmenopausal ER+ BC patients (NCT02463032)." (PMID 34066328, 2021). "Interestingly, in the era before the approval of ARSTAs, including abiraterone acetate and enzalutamide, most CRPC were AR-dependent PC (88.4%) with rare NEPC (6.3%) and DNPC (5.4%), although tumor phenotypic changes with a higher percentage of DNPC (23.3%) were observed in the contemporary era." (PMID 33921329, 2021). "Although AKT2 (v-akt murine thymoma viral oncogene homolog 2) was down-regulated in all three cancer nodules (x = −1.65 in “A”, −1.61 in “B” and −1.94 in “C”), AR (androgen receptor) was not affected and therefore the tumor did not regress as expected in the androgen-deprivation therapy." (PMID 34209090, 2021). "Patients with BXDC2-positive/AR-negative muscle-invasive bladder cancer had a significantly lower risk of disease-specific mortality, compared to those with a BXDC2-negative/AR-positive tumor." (PMID 33652650, 2021). "However, we did not examine the genetic profiles of our AR+ tumours to classify them into the LAR subtype." (PMID 35047068, 2021). "HDAC inhibition could downregulate AR protein levels and significantly induce PD-L1 expression by increasing the acetylation of the CD274 promoter, resulting in an immune-evasive microenvironment for tumor progression." (PMID 34830196, 2021). "However, not all castration resistance is dependent on AR signaling due to the diversity, plasticity, and heterogeneity of the tumor." (PMID 35008817, 2021). "Nevertheless, expression status of AR may be predetermined by progenitor cell populations in normal breast tissues, and AR may exert its roles in the tumor cell proliferation, but it may not be carcinogenic by itself." (PMID 33915941, 2021). "Importantly, the combination treatment was found to remain active in enzalutamide resistant CRPC models where AR downstream signalling was significantly impacted by enzalutamide treatment, although failed to impact tumour growth by itself." (PMID 34749299, 2021). "The majority of neoplasms were devoid of AR staining (data not shown)." (PMID 33574348, 2021).
tumor (continued). "As contributors to PCa heterogeneity, tumor cells that are strongly dependent on NF-κB signaling and cytokine production, but not on the AR pathway, may have a selective advantage in retaining caspase-8 expression." (PMID 34482382, 2021). "It is possible that these proteins might not have a predictive advantage over the general AR gene signature of tumor tissue itself." (PMID 34736512, 2021). "The results from AR staining revealed that AR expression was higher in the ccRCC primary tumors (n = 39) compared to the adjacent tissues (n = 26) and was significantly lower in RBM tissues (n = 20) than those found in the primary tumor group (p < 0.001) using Image‐Pro Plus software." (PMID 33783995, 2021). "It is unclear whether the enriched binding sites for FOXA1, HOXB13 and CDX2 are dependent or independent of AR activity in single cells from high-grade tumours." (PMID 34911933, 2021). "Importantly, neither the large variance in AR promoter methylation levels observed among the metastatic samples nor their AR amplification status showed any clear relationship to the tumor sample AR activity." (PMID 34193246, 2021). "Comparing with the control tissues without drug treatment showing AR staining mostly in the nuclei (95.4%), the tumor brain specimen after enzalutamide treatment showed a significantly higher percentage of cells with cytosol dominant distribution (96.7%) (p <0.05)." (PMID 34094902, 2021). "However, no direct evaluation of tumor cells was performed, such as assessment for downregulation of the AR-axis expected to occur following enzalutamide." (PMID 34588590, 2021). "Modern therapies against PC include androgen-deprivation therapy (ADT) and the treatment with antiandrogens as blockers of the AR pathway; however, after a few months to up to few years of treatment, tumours become castration-resistant and do not respond to antiandrogens therapy." (PMID 34685579, 2021). "But AR positivity is not the only determinant for tumor androgen pathway activity." (PMID 33915941, 2021). "Moreover, tumor regions containing KI67-positive cells with no nuclear AR were also positive for p-STAT3pY705." (PMID 34439133, 2021). "This might originate from the procedure of selecting all mCpG sites for analysis that correlated to the tumor AR activity on a continuous scale, i.e. the classifier was not originally built to dichotomize samples into two groups." (PMID 34193246, 2021). "Mouse models may help to elucidate factors in the tumor microenvironment or specific cell types of the host that contribute or prevent the switch from AR-positive to -negative disease." (PMID 33420371, 2021). "The use of accurate models that more faithfully resemble tumor heterogeneity such as patient-derived explants, PDX, and stromal co-culture with human organoids will be critical in defining the benefits of targeting metabolic pathways along with ADT or AR signaling inhibitors." (PMID 35582011, 2021). "Interestingly, an SGRM has been reported to decrease the GR-mediated PCa cell proliferation and CRPC tumor growth and viability without inhibiting the activity of the AR." (PMID 34137734, 2021). "Taken together, MEN1-KD in DU145 and PC3 cells promoted cell growth in an anchorage-independent manner and increased cell migration, suggesting that menin plays a tumor suppressive role in AR-independent PCa cell lines, unlike its oncogenic role in AR-dependent PCa cell lines." (PMID 34446068, 2021). "Interestingly, another study documented that MMP9, together with PIP5K1α, could interact with AR to promote its transcriptional activity on the downstream target cyclin A1, leading to enhanced growth of metastatic CRPC tumor." (PMID 34692685, 2021). "LAR TNBC is not the only subgroup to express or rely on the AR for tumor progression." (PMID 34201346, 2021). "In addition, AR status was an independent predictor for better outcome regardless of tumor size, grade, and nodal stage." (PMID 33014830, 2020).